CRP (C-reactive protein)
Diseases named in the same sentence as CRP in open-access papers (continued):
Sharing a sentence is not in itself a finding about the gene and the disease.
macrocytic anemia (11 papers, 2011 to 2026). Anemia that is characterized by increased red blood cell volume. "Serological investigation generally shows elevated inflammatory markers levels (as for erythrocyte sedimentation rate and C-reactive protein), macrocytic anemia (with normal copper, B12 and folate levels) combined with an inflammatory anemia." (PMID 36662445, 2023). "Blood analysis showed macrocytic anemia, 18500 leukocytes/mm3, normal enzymes, a C-reactive protein (CRP) of 303 mg/L, and a lactate level of 7.4 mmol/L." (PMID 24829816, 2013). "In the patients with normal C-reactive protein the inclusion of a couple of patients with different red blood cell pathologies, such as macrocytic anaemia, resulted in a normal mean corpuscular volume for the group." (PMID 21547258, 2011). "Laboratory evaluation showed macrocytic anaemia, elevated erythrocyte sedimentation rate (ESR), and C-reactive protein (CRP)." (PMID 39463879, 2024). "Laboratory studies demonstrated the presence of mild macrocytic anaemia and elevated inflammatory markers (ESR 125 mm/h and CRP 14.8 mg/dl)." (PMID 39411287, 2024). "Laboratory investigations showed macrocytic anemia (Hb 63 g/L and MCV 108.2 g/L) with markedly increased CRP, ESR, PCT, and SF." (PMID 35547205, 2022). "The laboratory examinations revealed macrocytic anemia (Hb, 6.9 g/dl; MCV, 108.3 fl), polymorphonuclear leukocytosis (WBC, 1.1×109/l), a platelet count of 7×109/l and a C-reactive protein level of 122.6 mg/l (normal, <8 mg/l)." (PMID 25789075, 2015). "Blood tests revealed an elevated C-reactive protein (CRP) of 150 mg/L, a slight leucocytosis of 10.9 109/L, macrocytic anaemia with a haemoglobin of 6.2 mmol/L, multiple vitamin and mineral deficiencies (folic acid, iron, zinc, magnesium and vitamin D) and normoglycaemia." (PMID 34433417, 2021). "The laboratory examinations revealed macrocytic anemia [hemoglobin (Hb), 8.3 g/dl; mean corpuscular volume (MCV), 106.6 fl], polymorphonuclear leukocytosis [white blood cell (WBC) count, 1.8×109/l], a platelet count of 3×109/l and a C-reactive protein level of 164.0 mg/l (normal, <8 mg/l)." (PMID 25789075, 2015).
Microscopic hematuria (11 papers, 2013 to 2025). Microscopic hematuria detected by dipstick or microscopic examination of the urine. "Laboratory investigations showed microhematuria and a C-reactive protein (CRP) of 40.2 mg/L (normal range (NR): <5 mg/L), with a slightly elevated creatine level of 1.47 mg/dL (NR: 0.7-1.3 mg/dL)." (PMID 41426816, 2025). "In our case, microscopic hematuria was observed on urinalysis on admission, and serum creatinine and CRP were also elevated, suggesting that this was an effect of acute tubulointerstitial nephritis." (PMID 39073524, 2025). "Microhematuria was disappeared and CRP became negative, however, the levels of proteinuria and renal function did not improve." (PMID 23537120, 2013). "Serum creatinine was stable (1.2 mg/dl), C-reactive protein (CRP) was negative, proteinuria(++) and microhematuria was absent." (PMID 23537120, 2013).
monoclonal gammopathy (11 papers, 2013 to 2025). A condition characterized by the abnormal presence of monoclonal immunoglobulins in the blood or urine. "Laboratory findings commonly include elevated inflammatory markers such as erythrocyte sedimentation rate (ESR) and C-reactive protein (CRP), and the presence of monoclonal gammopathy is a key diagnostic criterion." (PMID 39135817, 2024). "Another study reported falsely elevated CRP values in a case with monoclonal gammopathy, and that paraprotein-induced latex particle agglutination also caused raised sample turbidity, thus leading to a false increase in CRP levels." (PMID 37873776, 2023). "In patients with monoclonal gammopathies, C-reactive protein may be a more specific index of GCA compared with the ESR." (PMID 24359546, 2013). "The monoclonal gammopathy of undetermined significance resulted in falsely elevated CRP values in a case report, whereas an IgM-λ paraprotein was revealed to trigger falsely elevated CRP levels in an automated immunoassay using goat anti-CRP antibodies [1182,1183]." (PMID 37873776, 2023). "A search for an underlying monoclonal gammopathy was negative, and plasma concentrations of serum amyloid A protein (SAA) and C-reactive protein were in the normal range." (PMID 26790392, 2016).
Onset (11 papers, 2013 to 2025). The age group in which disease manifestations appear. "Patients with suspected new-onset infection were included in whom PCT, C-reactive protein (CRP), temperature, and leukocyte (WBC) values were measured on inclusion (t0) and data were also available from the previous day (t−1)." (PMID 27597981, 2016).
sickle cell disease (11 papers, 2013 to 2025). Sickle cell anemias are chronic hemolytic diseases that may induce three types of acute accidents: severe anemia, severe bacterial infections, and ischemic vasoocclusive accidents (VOA) caused by sickle-shaped red blood cells obstructing small blood vessels and capillaries. "High serum concentration of ultrasensitive C-reactive protein correlated negatively with both arylesterase (r = −0.179; P = 0.001) and paraoxonase activities (r = −0.229; P = 0.001) in the sickle cell disease group." (PMID 31366068, 2019). "This study assessed the diagnostic performance and prognostic properties of C-reactive protein (CRP), copeptin and cortisol in individuals with sickle cell anaemia (SCA)." (PMID 24223742, 2013). "Serum levels of copeptin, cortisol and CRP in patients with sickle cell anaemia (SCA) in steady state, VOC and controls." (PMID 24223742, 2013). "His erythrocyte sedimentation rate (ESR) and C-reactive protein (CRP) levels were both elevated, and proteins C and S were found to be low but within the expected range for someone with sickle cell disease." (PMID 23972124, 2013). "Also, the tSCE was not correlated with other independent variables such as the location of pain, sickle cell disease phenotype, CRP at admission, or blood count data." (PMID 33628254, 2021). "Serum levels of copeptin, cortisol and CRP in patients with sickle cell anaemia (SCA) and controls." (PMID 24223742, 2013). "Moreover, CRP has been noted as a marker of severity in Sickle Cell Disease (SCD), while another study showed that in asymptomatic steady-state HbSS individuals, elevated CRP could be protective in SCD, leading to better disease outcomes." (PMID 37873776, 2023). "Also, C-reactive protein, cortisol and copeptin are not good prognostic markers in sickle cell anaemia subjects in vaso-occlusive crisis." (PMID 24223742, 2013).
thalassemia (11 papers, 2011 to 2026). An inherited blood disorder characterized by a decreased synthesis of one of the polypeptide chains that form hemoglobin. "Quercetin reduced iron, ferritin, transferrin saturation, and high sensitivity C-reactive protein while it increased transferrin, which makes it a potent agent in improving the iron status in thalassemia." (PMID 38004496, 2023). "Sufficient plasma was available to measure CRP and ferritin in 8/9 students with α-thalassaemia trait and a raised ZPP." (PMID 31448286, 2019). "Corroborating previous studies, our research reported significantly higher CRP levels in thalassemia minor patients." (PMID 23497547, 2012). "In another study all adhesion molecules and CRP (C-reactive protein) increased in patients with thalassemia intermediate." (PMID 25356075, 2011). "Complete blood count including haemoglobin (Hb) concentration, serum ferritin (SF), C-reactive protein (CRP), and thalassemia were determined." (PMID 31992253, 2020). "Despite coexisting chronic hepatitis B and thalassemia, the patient’s immune function was not significantly impaired, with inflammatory markers such as PCT, CRP, and IL-6 remaining within normal ranges." (PMID 39728308, 2024).
Acute bronchitis (10 papers, 2015 to 2025). Inflammation of the large airways of the lung with rapid onset and short course usually associated with cough, mucus production, shortness of breath, wheezing, and chest tightness. "With regard to the associations of lung function and inflammatory factors with LRTIs, increased FEV1 (OR per SD = 0.80 [95% CI: 0.73, 0.88]) and FVC (OR per SD = 0.87 [95% CI: 0.79, 0.95]) lowered the risk of acute bronchitis, while elevated CRP augmented the risk." (PMID 39337223, 2024). "Based on the four criteria for the identification of a mediator, three factors (CRP, FVC, and FEV1) were identified as the mediators of the associations of BMI and WC on acute bronchitis." (PMID 39337223, 2024). "Studies have shown that CRP testing facilitated adequate antibiotic prescribing, which for patients with acute bronchitis decreased by half between 2008 and 2013 in Sweden." (PMID 32031035, 2020). "Since CRP testing is increasing and the prescription rate for acute bronchitis is decreasing at the same time, this might indicate that CRP is more often used to ensure the diagnosis of acute bronchitis and, in cases of acute bronchitis, motivate the choice to refrain from prescribing antibiotics." (PMID 32127365, 2020).
acute GVHD (10 papers, 2013 to 2023). "Our group reported that a significant elevation of CRP during the neutropenic period was associated with a subsequent incidence of acute GVHD." (PMID 24795865, 2014). "Several retrospective studies assessed the association between the elevation of CRP and transplant complications including acute GVHD." (PMID 24795865, 2014). "Thus, CRP seems to be associated with an adverse prognosis in acute GVHD." (PMID 32707721, 2020). "Recent studies have also evaluated the use of CRP for prognostication in allotransplant recipients who develop acute GVHD." (PMID 32707721, 2020). "Although baseline CRP values correlated with acute GvHD incidence (p = 0.001 for grade 2–4 acute GvHD; p = 0.002 for grade 3–4 acute GvHD), this association did not affect TRM or OS." (PMID 31632401, 2019). "NLR, MLR and PLR did not result in differences regarding duration of hospitalization, time to granulocyte reconstitution (> 0.5/nl), development of acute Graft versus Host disease (aGVHD), Cytomegalovirus reactivation, Epstein-Barr-Virus reactivation post-HSCT or C-reactive Protein (CRP) pre-HSCT." (PMID 36347969, 2022). "Although post-transplant CRP and ferritin levels were well correlated with sST2, these markers did not influence the cumulative incidence of acute GVHD (cut-off values were calculated by ROC analysis=CRP 6.0 mg/dL and ferritin 1700 mg/dL, respectively)." (PMID 31464120, 2020).
adenovirus infection (10 papers, 2018 to 2025). "In the Appenzeller study, it was noticed that adenovirus infection was associated with elevated CRP concentrations, indicating that HAdV infection triggers an immediate inflammatory host response resembling invasive bacterial infection." (PMID 39770373, 2024). "Adenovirus infection was similar to bacterial infection, most of which were characterized by increased white blood cell count and C-reactive protein." (PMID 33868812, 2021). "Unlike other documented respiratory viral infections had low WBC and CRP levels, human adenovirus infection typically results in high WBC and CRP levels, and the WBC and CRP levels had been compared between species B, C, and E in earlier studies." (PMID 33145348, 2020). "A KD diagnostic biomarker that is independent of CRP is necessary because CRP is sometimes high in patients with KD-mimic diseases, such as adenovirus infection." (PMID 34499692, 2021). "In addition, cases with adenovirus infection had abnormal glucose (6.25[5.2, 7.5] mmol/L) and CRP (13.45[3.9, 34.8] mg/L) levels." (PMID 34869087, 2021). "Cases with adenovirus infection had higher levels of CRP, which was consistent with Chen's study, revealing that elevated CRP levels were common in adenovirus infection, even without superimposed bacterial infection." (PMID 34869087, 2021). "In another recent study, we reported that the use of CRP as a supposed marker of disease aggressiveness was not predictive of the clinical course and thus not useful, or even potentially misleading, in children with adenovirus infection, another common epidemic infectious disease in small children." (PMID 40426750, 2025).
alexithymia (10 papers, 2019 to 2024). An agnosia that is a deficiency in understanding, processing, or describing emotions. "An association between alexithymia and higher circulation levels of acute phase proteins, especially C-reactive protein, has been reported by several studies." (PMID 31396292, 2019). "A statistical significant association was observed between alexithymia and inflammatory indices (ESR: P = .029, CRP: P = .043) and between alexithymia and clinimetric parameters (ptVAS, pVAS, GH, P < .0001 for all comparisons)." (PMID 30681555, 2019). "Furthermore, patient with high ESR and CRP values resulted positive to the presence of alexithymia, showing how a chronic condition of inflammation and pain, as in RA and in PsA, can conduce to an alteration of the psychiatric sphere." (PMID 30681555, 2019). "Also, in line with the “stress-alexithymia hypothesis”, there seems to be a clear relationship between the high presence of C-reactive protein in blood and alexithymia." (PMID 32082200, 2019). "In addiction, alexithymia TAS-20 values were higher in patients with high values of ESR and CRP." (PMID 30681555, 2019).
aortic atherosclerosis (10 papers, 2014 to 2025). A atherosclerosis that involves the aorta. "Human CRP transgene expression causes accelerated aortic atherosclerosis in Apoe–/– mice." (PMID 36602878, 2023). "The development of aortic atherosclerosis was positively correlated with C-reactive protein levels (IVW:p = 0.003, OR=1.203,95% CI:1.066–1.358)." (PMID 40779499, 2025). "In another study, transgenic rabbits with low and high CRP expression fed a high-cholesterol diet experienced similar coronary and aortic atherosclerosis." (PMID 28190984, 2016). "Circulating markers of inflammation (C-reactive protein (CRP), oxidized low-density lipoprotein (oxLDL), plasminogen activator inhibitor-1, lipid and glucose metabolism were evaluated together with coronary and aortic atherosclerosis after 22 or 43 diet-weeks." (PMID 26394837, 2015).
aortitis (10 papers, 2021 to 2025). Inflammation of the aorta. "Aortitis associated with G-CSF administration primarily presents as a systemic symptoms, manifesting as fever and increased levels of c-reactive protein (CRP)." (PMID 39744136, 2024). "Hence, in cases where high fever and elevated CRP levels persist after G-CSF administration, contrast CT should be considered when evaluating aortitis as a potential differential diagnosis." (PMID 40860786, 2025). "The mean CRP value was 82.8 mg/l ± 64 when performing FDG-PET/CT imaging of the aortitis group." (PMID 34462502, 2021). "Aortitis may have been a precursor to his aortic rupture given his persistently elevated erythrocyte sedimentation rate along with high initial white blood count and C-reactive protein." (PMID 36848911, 2023).
aseptic meningitis (10 papers, 2010 to 2026). Inflammation of the membranes surrounding the brain and spinal cord without a bacterial pathogen. "In addition, initial blood and CSF tests including WBC and CRP were often high confirming that it is often difficult initially to differentiate between bacterial and aseptic meningitis based on initial blood and CSF tests." (PMID 35611041, 2022). "Therefore it can be concluded that CRP can be considered as a sensitive reactive agent for differentiation of bacterial and aseptic meningitis." (PMID 32494342, 2020).
benign prostatic hyperplasia (10 papers, 2005 to 2025). A non-cancerous nodular enlargement of the prostate gland. "This study investigated the association between serum CRP level in men with benign prostatic hyperplasia (BPH) and lower urinary tract symptoms (LUTS) before and after medical treatment." (PMID 24454896, 2014). "Only 27 of 241 patients had CRP values > 10; one of these patients had a comorbidity that may have influenced the CRP level (benign prostate hypertrophy with chronic inflammation)." (PMID 29724244, 2018).
brain edema (10 papers, 2020 to 2026). Increased intracellular or extracellular fluid in brain tissue. "We wanted to know if miR-7-5p is also associated with MMP-9, ZO-1, occludin, TNF-α, IL-6, NLR, and CRP and if it jointly affects brain edema." (PMID 33392188, 2020). "CRP and ALT can reflect the severity of the disease, and their elevation suggests a likely deterioration of the patient’s underlying condition, increasing the risk of worsening brain edema." (PMID 39421568, 2024). "On the other hand, Hs-CRP can be triggered by cerebral edema after AIS and elevated CRP may further increase the risk of thrombosis." (PMID 35711907, 2022). "The primary outcome is the dichotomized Glasgow Outcome Score at 6 months and 12 months after injury, and the secondary outcomes are the Glasgow Coma Scale, the volume of traumatic brain edema, the serum levels of C-reactive protein and interleukin-6, and the Modified Barthel Index." (PMID 35212308, 2022). "poor outcome, age, platelet-lymphocyte ratio (PLR), C-reactive protein (CRP), Hunt-Hess grade, mRS score, and World Federation of Neurological Surgeons score (WFNS), complications (intracranial infection, cerebral edema, hydrocephalus, and complications by DCI." (PMID 40661949, 2025). "We obtained preliminary conclusions from serum indicators of clinical patients that miR-7-5p may affect brain edema, but it does not affect MMP-9, ZO-1, occludin, IL-6, TNF-α, NLR, and CRP expression to affect the formation of brain edema." (PMID 33392188, 2020).
carditis (10 papers, 2010 to 2025). "At 12 months, CRP had fully normalized (p>0.05 vs. controls) and cTnI approximated control values (p>0.05), whereas NT-proBNP remained modestly elevated in the carditis group (p<0.05)." (PMID 41446443, 2025). "At diagnosis, NT-proBNP, CRP, and cTnI concentrations were significantly higher in the carditis group than in healthy controls (p<0.001)." (PMID 41446443, 2025). "At 12 months, CRP and cTnI had normalized (p > 0.05 vs. controls), while NT-proBNP remained mildly elevated in the carditis group (p < 0.05)." (PMID 41446443, 2025). "These sections were immunostained with a C-reactive protein (CRP) antibody, a well-established marker for carditis." (PMID 39338441, 2024).
cataract (10 papers, 2021 to 2026). Partial or complete opacity of the crystalline lens of one or both eyes that decreases visual acuity and eventually results in blindness. "Elevated levels of markers such as C-reactive protein (CRP) and interleukin-6 (IL-6) have been implicated in the pathogenesis of cataracts." (PMID 38638289, 2024). "Venous blood samples from 104 cataract patients and 100 healthy subjects revealed significantly higher levels of interleukin-6 (IL-6), IL-1β, C-reactive protein (CRP) and tumor necrosis factor-1α (TNF-1α) in the cataract group than in the healthy group." (PMID 39556543, 2024). "Higher levels of CRP were in turn observed in the blood plasma of males who later developed cataracts, compared to in those who remained cataract-free." (PMID 37892980, 2023). "Moreover, the leptin levels were positively correlated with the CRP levels in all cataract patients (r = 0.83, p = 0.011), including females (r = 0.95, p = 0.015)." (PMID 37892980, 2023). "SHAP analysis identified drusen severity and lens opacity (LOCS III) as dominant ocular predictors, while C-reactive protein (CRP) and smoking were critical systemic contributors." (PMID 42052023, 2026).
cognitive disorder (10 papers, 2013 to 2025). A disease affects cognitive processes. "Thus, serum CRP, RAGE, and myo-inositol in the left hippocampus are candidate biomarkers for cognitive diseases that warrant validation in future studies." (PMID 23978069, 2013).